CD47 (CD47 molecule)
Diseases named in the same sentence as CD47 in open-access papers (continued):
Sharing a sentence is not in itself a finding about the gene and the disease.
tumor (continued). "PD-L1 is highly expressed on the surface of tumor cells, and CD47 (Integrin-Associated Protein) is expressed in tumor cell-surface to serve as an immune checkpoint, both of which can promote tumor immune evasion." (PMID 32408880, 2020). "They proposed that the radioprotective effect of CD47 blockade rescued blood-vessel loss from irradiation damage, allowing more immune cells (such as macrophages) to enter the tumor and suppress its growth." (PMID 31547758, 2020). "Tumor-infiltrating CD8+ T lymphocytes are associated with favorable survival in multiple tumor types while B7-H3 or CD47 expression is correlated with poor survival of cancer patients." (PMID 32544882, 2020). "In a mouse model of T-ALL overexpressing Myc and in DLBCL cell lines, Myc was associated with high CD47 expression on tumor cells, suppressing recruitment of macrophages and tumor phagocytosis." (PMID 33092116, 2020). "Prophylactic CD47−/− whole tumor cell vaccination also caused a two-fold reduction in tumor growth rates and five-fold reduction in size in the tumors that escaped." (PMID 31882679, 2019). "Up-regulation of CD47 expression in human cancers negatively regulates anti-tumor immunity through suppression of phagocytosis, and it has been associated with tumor growth and dissemination." (PMID 32082304, 2019). "We found that MNNG/HOS tumor cells underwent significant loss of cell viability in the presence of macrophages and CD47 mAb (60%) when compared to co-cultures treated with control mAb (15%)." (PMID 30674867, 2019). "CD47 monoclonal antibodies (mAbs) inhibit the interaction between CD47 and SIRPα, and thereby activate tumor-associated macrophages (TAMs) to phagocytize cancer cells." (PMID 30674867, 2019). "Mechanistically, miR‐708 directly binds to cluster of differentiation 47 (CD47), and regulates tumour‐associated macrophage‐mediated phagocytosis." (PMID 31273952, 2019). "Radiation has been shown to induce anti-tumor immune response and associated with a dose-dependent decrease in the surface expression of CD47 on HPV(+) HNSCC cells, resulting in improved clearance of tumorous cell, in vitro and in vivo." (PMID 31861233, 2019). "We further show that PDAC patients with high tumor expression of CD47 and high tumor-infiltrating macrophages were associated with poor clinical outcomes." (PMID 31771616, 2019). "We found that patients whose tumor cells had high expression of CD47 and PD-L1 (CD47high /PD-L1high) were associated with worse OS compared to low CD47 and PD-L1 expression (CD47low/PD-L1low) (p = 0.003)." (PMID 31771616, 2019). "Upregulation of IDO1 has been linked to high number of regulatory T-cells in tumours and increased M2/M1 ratio while high CD47 has been linked to inhibition of macrophage-mediated phagocytosis both leading to tumour immunosuppression." (PMID 31358801, 2019). "Cluster of differentiation 47 (CD47), also known as integrin-associated protein, is a transmembrane immune checkpoint protein expressed on the cell surface of tumor cells and hematopoietic cells." (PMID 31540045, 2019). "Here, we show that tumor-associated microglia are capable of in vivo tumor cell phagocytosis in response to anti-CD47 blockade." (PMID 30602457, 2019). "miR-708 was shown to directly bind the CD47 gene regulating the expression of this molecule and the tumor-associated macrophage-mediated phagocytosis." (PMID 31921125, 2019). "Our results also showed that low IDO1 and CD47 in tumour cells associated with improved prognosis, further supporting the importance of TAMs." (PMID 31358801, 2019). "RRx-001 is a minimally toxic small molecule that dually downregulates CD47 on tumor cells and SIRPα on macrophages and triggers tumor associated macrophage phagocytosis of tumor cells in vitro and in vivo." (PMID 30400835, 2018). "Overexpression of CD-47 causes the tumor cells escape from immunosurveillance and results in tumor progression." (PMID 29861465, 2018).
tumor (continued). "RRx-001 is a Phase 3-ready small molecule innate immune checkpoint inhibitor, which triggers tumor associated macrophage phagocytosis of high-expressing CD47 tumor cells." (PMID 30400835, 2018). "Blocking the CD47-SIRPα axis is thus an attractive approach to foster tumor cell killing by tumor-associated macrophages (TAMs) and boost cross-priming of anti-tumor T cells by dendritic cells (DC)." (PMID 30400822, 2018). "Consistent with the role of TSP1 in recruiting macrophages into tumors, the number of F4/80+ tumor-infiltrating macrophages was significantly lower in CD47-deficient than WT mice." (PMID 27283989, 2017). "The culture supernatant of the tumor cells from WT mice was significantly more effective in recruiting macrophages than that from CD47-deficient mice." (PMID 27283989, 2017). "Because CD47−/− tumor cells are subject to immune rejection in WT mice, we injected these tumor cells into CD47-deficient mice and examined tumor growth and angiogenic potential within 9 days after tumor cell inoculation." (PMID 27283989, 2017). "We found that CD47 deficiency in tumor stromal endothelial cells enhances angiogenesis, leading to suppressed tumor necrosis formation and accelerated tumor progression." (PMID 27283989, 2017). "Although the two groups of mice had similar incidence and latency period for palpable tumor formation, RM1 tumor grew significantly more aggressively in CD47-deficient than in WT mice." (PMID 27283989, 2017). "Tumor cell suspensions were prepared from WT or CD47-deficient mice, cultured for 20 hrs, and tested for the ability to recruit mouse macrophages using the Transwell plate system." (PMID 27283989, 2017). "While CD47 is implicated in the regulation of cancer cell invasion and metastasis, its most well-studied and important function related to tumor development is prevention of phagocytosis via ligating with SIRPα on the surrounding phagocytes." (PMID 28077173, 2017). "And CD47 is a protein inhibiting the cytotoxic and phagocytic activity of T cells and macrophages which is associated with tumor cell immune escape." (PMID 27935872, 2017). "Loss of CD47 induces phagocytosis by macrophages in vitro and blocks tumor development and metastasis in vivo." (PMID 26941482, 2016). "Elevated CD47 expression limits the killing of tumor cells through its interaction with SIRPα, whereas loss of CD47 triggers phagocytosis." (PMID 27671753, 2016). "Human tumors grown in immunodeficient NOD-SCID mice that express a variant of SIRPα that binds human CD47 with high affinity have been used to test the ability of B6H12 to enhance macrophage-mediated clearance of human tumor xenografts." (PMID 26840086, 2016). "While it sensitizes the tumor to ionizing radiation, CD47 deficiency concomitantly confers radioprotection to normal tissues through activation of autophagy." (PMID 26578962, 2015). "A recent report indicates that CD47/SIRPα axis plays an important role by reducing mature DCs and attracting tumor associate macrophages." (PMID 26573233, 2015). "Tumor cells express high levels of CD47 to avoid phagocytosis by tumor-associated macrophages, and CD47 expression has been shown to be required for the survival, growth and metastasis of hematopoietic and solid tumors." (PMID 25685060, 2015). "CD47 blockade of tumor cells and normal tissues is, respectively, associated with immune mediated tumor rejection and radioprotection." (PMID 22891162, 2012). "Loss of DNAJC13 may lead to CD47 internalization or degradation, rendering tumor cells more susceptible to innate immune clearance." (PMID 41601654, 2026). "Additionally, it remodeled TME by repolarizing tumor-associated macrophages (TAMs) toward a pro-inflammatory phenotype and downregulating CD47-mediated immune escape." (PMID 42129801, 2026).
tumor (continued). "In contrast, combining DNAJC13 knockout with anti-CD47 therapy significantly impaired tumor growth, suggesting that partial loss of CD47 primes tumors to respond more robustly to therapeutic blockade, possibly by enhancing the sensitivity of tumor cells to Fc-mediated effector mechanisms." (PMID 41601654, 2026). "Together, these results demonstrate that loss of DNAJC13 sensitizes tumor cells to macrophage-mediated phagocytosis, likely by disrupting CD47-dependent inhibitory signaling, and reinforces the functional relevance of DNAJC13 as a modulator of innate immune evasion." (PMID 41601654, 2026). "Moreover, in vivo studies demonstrated that DNAJC13-deficient tumors were more sensitive to anti-CD47 antibody therapy, resulting in reduced tumor growth and increased immune activation, as reflected by decreased Ki-67 and elevated cleaved caspase-3 staining." (PMID 41601654, 2026). "CD47, initially identified as an integrin‐associated protein binding to integrin αvβ3 in placental tissue and platelets, has raised questions regarding its interaction with αvβ3 in tumor cells." (PMID 41168993, 2026). "To elucidate the mechanisms underlying tumour immune evasion and guide the design of targeted interventions, we first performed comprehensive pathway enrichment and network analyses focused on genes functionally associated with PD-L1 and SIRPα/CD47 signalling." (PMID 41402667, 2025). "In addition to its role in immune evasion, CD47 expression has been linked to various clinicopathological features, including tumor differentiation, lymph node metastasis, and TNM staging." (PMID 40765033, 2025). "This discrepancy may be attributable to the observation that CD47‐mediated immune evasion is contingent on its interaction with SIRPA on tumor‐associated macrophages." (PMID 41354057, 2025). "The increased release of CD47 associated with EVs by activated T and B cells in the tumor microenvironment could also create a sink that limits therapeutic CD47 antibody binding to tumor cells and merits further study." (PMID 40943300, 2025). "Although CD47 is overexpressed on PDAC tumor cells compared to adjacent normal epithelium, blockade of CD47 could pose a risk for auto-immunity such as hemolysis." (PMID 40358156, 2025). "Integrating inflammatory biomarkers with PSA or mpMRI may enhance diagnostic accuracy and guide personalized immunotherapeutic strategies, such as targeting NF-κB or tumor-associated macrophages via CDK12/13 inhibition or CD47 blockade." (PMID 41293737, 2025). "Besides, nanoparticles (gCM-MNs) not only inhibit the CD47-SIRPα axis but also repolarize tumor-associated macrophages to M1 macrophages." (PMID 40835598, 2025). "By targeting both CD47 and PD-L1 with a higher binding affinity to PD-L1, IBI322 more selectively blocks CD47 on tumor cells expressing both CD47 and PD-L1 than tumors expressing CD47 alone, thus minimizing adverse effects caused by the blockade of CD47 expressed on healthy red blood cells." (PMID 40565299, 2025). "Similarly, CD47 has been implicated in promoting tumor aggressiveness through its function in immune evasion, notably by inhibiting immune cell activity within the tumor microenvironment." (PMID 39857116, 2025). "It is questionable though, whether macrophages alone are able to eradicate a whole tumor, since tumor regression caused by approaches to enhance macrophage phagocytosis (e.g., using anti-CD47) often requires intact T cell responses." (PMID 40098954, 2025). "The CD47–SIRPα axis, which suppresses phagocytic clearance, has also been linked to diminished survival, while preclinical blockade of this pathway improves anti-tumor immunity." (PMID 41346390, 2025). "Notably, the high expression of CD47 in various tumor cells makes it a hallmark biomarker for malignant tumors." (PMID 40129966, 2025).
tumor (continued). "CD47 is a tumor-associated antigen binds to and activates signal regulatory protein α (SIRPα), an inhibitory protein expressed on the surface of macrophages, allowing tumor cells to evade innate immune surveillance." (PMID 40735642, 2025). "CD47 was identified in association with integrins using pull-down assays of tumor lysate." (PMID 41511354, 2025). "As bacterial density increases, the LuxI-generated signal accumulates to a threshold, activating the pLux promoter and triggering expression of the bacterial lysis protein ΦX174E, which in turn causes cell lysis and releases anti-CD47 nanobody at the tumor site." (PMID 41182556, 2025). "Therefore, radiotherapy combined with CD47/SIRPα axis-associated immunotherapy can further promote anti-tumor efficiency, which is mainly associated with reshaped immune-activated irradiated tumor microenvironments." (PMID 40835598, 2025). "In addition, combination therapy with CD47 blockade enhanced ADCC-mediated tumor cell killing of IgA1 and the HSA-fused IgA1 variants." (PMID 40041621, 2025). "Furthermore, the engineered EVs expressing CD47 competitively bind with signal regulatory protein α, thereby enhancing the phagocytosis of tumor cells by tumor-associated macrophages." (PMID 38675228, 2024). "However, current monoclonal antibody targeting CD47‐SIRPα axis is associated with on‐target off‐tumor and antigen sink effects, which significantly limit its potential clinical application." (PMID 38477522, 2024). "Morphology, shape, and, in particular, the relatively small size of the T cells (as compared with tumor cells) may contribute to their high susceptibility to phagocytosis once CD47 is blocked by CV1-Fc." (PMID 38828721, 2024). "CD47 is highly expressed in various tumor types and is associated with poor prognosis." (PMID 39201801, 2024). "Furthermore, blocking CD47 confers radioresistance to ECs in vitro and protects soft tissue, bone marrow, and tumor-associated leukocytes in irradiated mice." (PMID 38426109, 2024). "Importantly, CD47 expressed by tumor cells has been implicated in the switch in the development and function of the myeloid compartment within tumors." (PMID 38577107, 2024). "Interestingly, the downregulation of CD47 in tumor-associated ECs increases angiogenesis, vascular integrity and stability, VEGF-A and VEGFR2 expression and promotes tumor growth." (PMID 38426109, 2024). "Furthermore, inhibition of the CD47-SIRP1α pathway, a molecule expressed on the surface of all cells and associated with a wide range of intercellular activities, is a useful anti-tumor therapeutic strategy." (PMID 39678502, 2024). "We also noted that tumor‐associated innate populations expressed high levels of CD47 and PD‐L1, suggesting that local CD47 × PD‐L1 BisAb engagement may also regulate CD8+ T cell activity." (PMID 39584189, 2024). "Moreover, RRx-001 is an anticancer drug candidate in phase III clinical trials, which inhibits CD47 expression and polarizes tumor-associated macrophages from a low phagocytic M2 phenotype to a high phagocytic M1 phenotype." (PMID 38275876, 2024). "Moreover, blockade of CD47-SIRPα axis results in converting tumor associated macrophages (TAMs) into an anti-tumor state and consequently provides augmented phagocytosis and suppressed growth of the tumor." (PMID 38892394, 2024). "An alternative strategy is to target SIRPα, which has a much more restricted pattern of expression than CD47 and could potentially reduce the risk of on-target, off-tumor toxicities." (PMID 38319147, 2024). "However, tumor heterogeneity causes the amount of CD47 to vary from cell to cell, leading to targeting failure." (PMID 38520730, 2024). "A combination of Dinutuximab and anti-CD47 antibodies results in the recruitment of tumor-associated macrophages (TAMs) to mediate robust and durable anti-tumor responses, which might expand the clinical use of anti-GD2 mAbs to other GD2+ diseases beyond NB." (PMID 39620227, 2024).
tumor (continued). "Thus, our study revealed several tumor cell-intrinsic mechanisms underlying the resistance/efficacy of CD47-SIRPα ICB, and provided strategies to overcome resistance or enhance efficacy, shedding light on the clinical development of CD47-SIRPα ICB." (PMID 38982116, 2024). "Another obvious question is whether infiltration by TAMs is associated with any differences in the expression of CD47 in tumor cells." (PMID 39201801, 2024). "In this issue of the JCI, Vaccaro and colleagues utilized an innovative drug screen approach to demonstrate that targeting driver oncogenic signaling pathways concurrently with anti-CD47 sensitizes tumor cells, causing them to undergo macrophage-induced phagocytosis." (PMID 38690738, 2024). "Further, higher CD47 expression could be a proxy of predominant immunosuppressive tumor associated macrophages." (PMID 37468567, 2023). "Additionally, ECs exhibit radioresistance in vitro and protect soft tissue, bone marrow, and tumor-associated leukocytes in irradiated mice by blocking CD47 signaling." (PMID 37666809, 2023). "Interestingly, the downregulation of CD47 in TECs has been associated with increased angiogenesis, suppressed tumor necrosis formation, and accelerated tumor growth." (PMID 37666809, 2023). "Previously, we have reported superior antagonistic activity of bsAbs towards cancer cells that co-overexpress a tumor-associated antigen of interest and immune checkpoints PD-L1 or CD47, which was most likely attributable to the enhanced avidity associated with the tetravalent bsAb-format." (PMID 37509310, 2023). "Nevertheless, CD47 is also highly expressed in various tumors 13, through which cancer cells release anti-phagocytic signals to masquerade as normal cells, thereby causing immune escape and promoting tumor progression." (PMID 37781520, 2023). "The study mainly focused on the CD47 molecule associated with macrophages and tumor immunity." (PMID 37545625, 2023). "Anti-CD47 mAbs cause tumor cells to die via a process unrelated to caspases." (PMID 38033495, 2023). "Since HGSOC tumor cells express high levels of the “don ́t eat me” ligand CD47, and high CD47 expression is associated with a worse prognosis in metastatic ovarian tumors, CD47 represents a promising target to increase antibody-mediated phagocytosis through diminished “don ́t eat me” signals." (PMID 37876933, 2023). "However, an alternative method has emerged involving a bispecific antibody that can target CD47 and tumor-associated antigens at the same time." (PMID 36960057, 2023). "Patients with KRAS mutations showed a higher level of CD47 expression on the tumor cell surface." (PMID 36413402, 2023). "A high level of leucine rich repeats and immunoglobulin like domains 2 (LRIG2) expression, which is linked with GBM progression and poor prognosis, has been shown to increase CD47 expression, and CD47 expression has been shown to be associated with a higher tumor grade and worse clinical outcomes." (PMID 36768342, 2023). "Moreover, high mRNA and protein expression of CD47 was associated with advanced tumor stage, metastasis, recurrence, and/or survival in the majority of NSCLC and SCLC studies that we assessed." (PMID 37958404, 2023). "This study also provides insights into the release of the tumor immune escape caused by CD47-SIRPα." (PMID 37375166, 2023). "Combining CD47 inhibitors with PD-1/PD-L1 inhibitors or cytotoxic T-lymphocyte–associated antigen 4 (CTLA-4) inhibitors may enhance the anti-tumor immune response by promoting T cell activation and reducing immune suppression in the TME." (PMID 38188674, 2023).